CD109 (CD109 molecule)
Diseases named in the same sentence as CD109 in open-access papers (continued):
Sharing a sentence is not in itself a finding about the gene and the disease.
glioblastoma (continued). "Furthermore, analysis of the gene expression data from the human brain tumor immune microenvironment demonstrated the highest CD109 expression in the monocyte-derived macrophages, yet the expression did not increase in glioblastomas compared with the nontumor reference samples." (PMID 33986188, 2021). "In accordance with our findings, high CD109 mRNA expression associated with poorer survival in the data sets of lower grade gliomas (TCGA LGG) and when glioblastoma and lower grade gliomas were combined, but not in glioblastomas alone (TCGA GBM)." (PMID 33986188, 2021). "We recently reported that in glioblastoma patients treated with bevacizumab and irinotecan or with bevacizumab alone, PFS and OS were significantly increased in patients with baseline counts of CD109+CECs higher than 41.1/mls, (1stquartile), while no prognostic factor was associated to CD146+CECs." (PMID 25506915, 2014).
glioma (15 papers, 2018 to 2025). A benign or malignant brain and spinal cord tumor that arises from glial cells (astrocytes, oligodendrocytes, ependymal cells). "Higher transcript levels in the NP were also found for CD101 encoding the transmembrane glycoprotein V7, a prognostic marker for gliomas, and CD109 encoding a protein that negatively regulates TGFβ signaling and is involved in tumorigenesis." (PMID 36406265, 2022). "More specifically in gliomas, CD109 has been proposed as a marker of perivascular GSCs, and very recent reports indicate a clear association between CD109 and GSC stemness maintenance and disease recurrence." (PMID 33986188, 2021). "Here, we describe a clinically relevant association of CD109 with the STAT3 activation in glioma samples and patient-derived GSCs." (PMID 33986188, 2021). "Using a large cohort of clinical glioma samples and patient-derived GSCs, we established the association between CD109 and STAT3 phosphorylation." (PMID 33986188, 2021). "In another study, CD109 expression was found to promote the progression of glioma and tumour metastasis and resistance via the EGFR pathway expression." (PMID 40227788, 2025). "CD109-positive cells sorted from glioma or triple-negative breast cancer show resistance to chemotherapy compared with CD109-negative cells." (PMID 37373457, 2023). "Particularly, among the proteins over-expressed in GBM-sEVs, we noted the glioma-associated extracellular matrix antigen Tenascin C (TNC), the stemness-associated CD109 antigen, the tumor-associated CD44 antigen, the Ras suppressor protein 1 (RSU1)." (PMID 36009432, 2022). "CD109 is already considered a marker of the glioma cells that populate the perivascular tumor, promoting its progression by suppressing TGF-β signalling." (PMID 33469081, 2021). "Recently, CD109/ (Tep1 in Drosophila) was shown to be a novel upstream regulator of YAP/TAZ during glioma growth." (PMID 32457905, 2020). "We further show that the recently identified Yki modifier, Tep1 (Drosophila ortholog of CD109) is a modifier of glioma phenotype due to its effect on NSC number." (PMID 32457905, 2020). "More recently, CD109 was found highly expressed in penile squamous cell carcinoma and to be a key regulator of the progression of lower-grade glioma and therefore a potential molecular target for therapy." (PMID 29731998, 2018). "Given the conservation of gene functions, Drosophila glioma models may prove informative in further understanding the Tep (CD109) and Yki (YAP/TAZ) in tumor growth and progression." (PMID 32457905, 2020). "In tumor tissues, CD109 was immunohistochemically detected in SCCs as well as urothelial carcinomas, malignant melanomas, basal-like breast carcinomas, myxofibrosarcoma, epithelial sarcomas and glioma." (PMID 29625613, 2018). "In a Drosophila glioma model, it was also shown that TEP1 (Drosophila ortholog of human CD109) regulates the Drosophila Yki pathway (ortholog to Yap/Taz)." (PMID 33738281, 2021). "qRT-PCR with 2 additional edge- and core-derived glioma sphere models (Edge- and Core-derived g1053 spheres and g0573 spheres) showed that both PLAGL1 and CD109 were higher in the core-derived, yet CD133 was up in the edge-derived, glioma spheres in vitro." (PMID 33392508, 2020). "Similarly, in GBM, NDUFA6-DT demonstrates a negative correlation with SUMF1, CD109, MUC11, and MYBPH, which are all implicated in promoting glioma progression." (PMID 38674418, 2024). "Moreover, Thymosin beta-4 (TMSB4X) and CD109, and 14.3.3 and HSP90 alpha could discriminate among other brain tumors and low-grade gliomas plus glyoneuronal tumors/pilocytic astrocytoma, or embryonal tumors/medulloblastoma." (PMID 33469081, 2021).
lung adenocarcinoma (13 papers, 2018 to 2026). A carcinoma that arises from the lung and is characterized by the presence of malignant glandular epithelial cells. "In human lung adenocarcinoma cell lines, CD109 overexpression was associated with the ability of migration and metastasis by activating the Jak-Stat3 signaling." (PMID 36712866, 2022). "Our recent study found that CD109 expression was associated with aggressiveness and metastasis of lung adenocarcinomas." (PMID 33375719, 2020). "Our findings are in agreement with another report showing that elevated CD109 levels activate EGFR-AKT-mTOR signaling in lung adenocarcinoma cells." (PMID 40317079, 2025). "CD109 acts as a pro-metastatic factor in lung adenocarcinoma by activating the JAK/STAT3 signaling pathway, which is also integral to inflammation and immune responses." (PMID 39990858, 2024). "Both, CD109 and DSG2 are genetic risk factors, linked to reduced overall survival in lung adenocarcinoma patients (subtype of NSCLC)." (PMID 38562713, 2024). "CD109 is highly expressed in lung adenocarcinoma, where it promotes tumor progression, metastasis, and is associated with poor patient outcomes." (PMID 39990858, 2024). "Further studies showed that CD109 promoted lung adenocarcinoma invasion and metastasis in vivo through TGF-β signaling pathway." (PMID 36814485, 2023). "For example, it was recently reported that CD109 drives metastasis in lung adenocarcinoma by modulating Jak/Stat3 signaling." (PMID 35954339, 2022). "We previously found that cluster of differentiation 109 (CD109) was upregulated in lung tumor tissues, and CD109 overexpression was correlated with the invasive and metastatic capacities of lung adenocarcinoma cells." (PMID 33375719, 2020). "We previously identified that CD109 is upregulated in lung adenocarcinoma cells, and suppression of CD109 inhibits the metastatic capacity." (PMID 33375719, 2020). "Conversely, CD109 overexpression increased tumorsphere formation in CL1-3 cells, indicating that CD109 expression is crucial for stem-like properties in lung adenocarcinoma cells." (PMID 33375719, 2020). "Our data were in line with previous findings that CD109 promotes YAP signaling in lung adenocarcinoma cells." (PMID 33375719, 2020). "Although knockdown of CD109 in human keratinocytes and lung adenocarcinoma cells downregulates STAT3 signaling in vitro, the CD109-deficient mice displayed opposite results." (PMID 29625613, 2018). "Furthermore, CD109 knockdown in lung adenocarcinoma reduced chemotherapy resistance and inhibited tumor metastasis in mice." (PMID 37373457, 2023). "For example, the pathways reported potentially to mediate CD109′s tumorigenic effect in lung adenocarcinoma include JAK-SAT, Hippo-YAP, and EGFR-AKT-mTOR, but their relative significance and potential cross-talk in mediating CD109 action in lung adenocarcinoma are poorly understood." (PMID 35954339, 2022). "Moreover, CD109 overexpression significantly promoted the migratory and invasive capacities of CL1-3 cells, confirming that CD109 expression is responsible for EMT traits in lung adenocarcinoma cells." (PMID 33375719, 2020). "In lung adenocarcinoma patients, coexpression of CD109 and YAP rendered a worse survival prognosis." (PMID 33375719, 2020). "Previous research revealed that CD109 promoted EMT process and stemness in lung adenocarcinoma, and CD109 was considered as a potential therapeutic target." (PMID 36712866, 2022). "This evidence implies the important role of CD109 in EGFR-TKI therapies, and it also highlights translational relevance of CD109 as a diagnosis and therapeutic target in lung adenocarcinoma patients." (PMID 33375719, 2020). "Our present study further discovered that CD109 regulates EMT and stemness of lung adenocarcinoma cells via a YAP-dependent manner." (PMID 33375719, 2020).
lung adenocarcinoma (continued). "Furthermore, CD109 maintains cancer stem-like properties or promotes tumorigenicity and metastasis by interacting with EGFR in lung adenocarcinoma, cervical squamous cell carcinoma, and HNSCC." (PMID 37373457, 2023). "In the present study, we identified that CD109 was upregulated in metastatic lung adenocarcinoma cells, and elevation of CD109 was correlated with epithelial-to-mesenchymal transition (EMT) traits in patients with lung adenocarcinoma." (PMID 33375719, 2020). "In non-SCC cancers such as lung adenocarcinoma, several recent reports show that CD109 exhibits a pro-tumorigenic role, even though those reports vary as to the specific intracellular pathways that may mediate the CD109 effects." (PMID 35954339, 2022). "Moreover, lung adenocarcinoma patients with higher coexpression of CD109 and YAP showed worse overall and disease-specific survival probabilities, underpinning the potential role of CD109 possibly serving as prognostic and therapeutic targets for lung adenocarcinoma patients." (PMID 33375719, 2020).
breast carcinoma (10 papers, 2012 to 2025). "To understand the role of CD109 in cancer, we used whole cell membrane proteomics and identified the cell surface CD109 as a metastasis-associated protein in breast cancers and melanomas." (PMID 33986188, 2021). "Soluble CD109 shed from breast cancer cells also promoted malignant growth in 3D organotypic culture." (PMID 36768435, 2023). "In breast cancer, CD109, ID4, and ST8SIA1 are involved in the maintenance of stem cell phenotype, whereas NR4A1 promotes TGF-β-induced EMT and invasion." (PMID 32679794, 2020). "According to Kaplan–Meier plotter, low expression of CD109, ID4, NR4A1, and SYCP3 is associated with poor RFS in breast cancer patients." (PMID 32679794, 2020). "While CD109’s exact role in TNBC remains unclear, its association with breast cancer stem-like cells suggests a potential involvement in inflammation in TNBC leading to high mortality and tumor progression." (PMID 39990858, 2024). "Consistent with this notion, CD109-positive basal-like breast carcinoma shows reduced fat invasion as compared to the CD109-negative counterparts, suggesting that CD109 expression may affect biological properties of cancer cells." (PMID 31695056, 2019). "CD109 protein expression is much higher in TNBC than in non-TNBC, and CD109 expression correlates with a higher histological grade and poorer post-operative survival in breast cancer patients." (PMID 36768435, 2023). "In agreement, we also found CD109 overexpression in the triple negative EGFR overexpressing breast cancer cell line MDA-MB-468, but not in the ER-, PR-, HER2 overexpressing cell line SKBR-3." (PMID 29731998, 2018).
epithelioid sarcoma (8 papers, 2013 to 2025). An aggressive malignant neoplasm of uncertain differentiation, characterized by the presence of epithelioid cells forming nodular patterns. "The expression of CD109 has also been reported in cancer stem-like cells/cancer-initiating cells (CSCs/CICs) in the epithelioid sarcoma cell line ESX, and was found to be associated with poor prognosis in patients with soft tissue sarcoma." (PMID 29731998, 2018). "Additionally, CD109 was elevated in aldehyde dehydrogenase 1 (ALDH1)-positive epithelioid sarcoma cells, and CD109 expression increased ALDH1 activity by suppressing the TGF-β/Smad signaling pathway." (PMID 33375719, 2020). "In conclusion, CD109 might be a CSC/CIC marker in epithelioid sarcoma." (PMID 24376795, 2013). "CD109, a negative regulator of TGF-β signalling is a possible prognostic biomarker in epithelioid sarcoma and penile squamous cell carcinoma." (PMID 36299526, 2022). "Recently, some researchers suggested that high expression of CD109 regulates the phenotype of cancer stem-like cells/cancer-initiating cells (CSCs/CICs) in the novel epithelioid sarcoma cell line ESX and may be a CSCs/CICs biomarker in epithelioid sarcoma." (PMID 27419372, 2016).
lung carcinoma (8 papers, 2015 to 2026). "Clinically, CD109 expression is associated with the YAP signature, and coexpression of CD109/YAP renders the worst survival outcome in lung cancer patients." (PMID 33375719, 2020). "CD109 is reported as a potential diagnostic and therapeutic factor for lung cancer metastasis." (PMID 35978854, 2022). "Additionally, the GSEA revealed significant associations between CD109 and YAP signatures in lung cancer patients, and positive correlations of CD109 and stem-like signatures, confirming the in vitro findings that CD109 regulates YAP signaling." (PMID 33375719, 2020). "Our study reveals the molecular mechanism underlying CD109 in lung tumor aggressiveness, and CD109 could be a potential diagnostic and therapeutic target for lung cancer patients." (PMID 33375719, 2020). "For example, upregulation of CD109 is associated with oral cancer and lung cancer." (PMID 26025379, 2015). "CD109 could be a potential diagnostic and therapeutic target for lung cancer patients." (PMID 33375719, 2020). "In lung cancer metastasis, CD109 expression led to the activation of the Jak‐Stat3 signalling pathway." (PMID 36134447, 2022). "For LC-cell line markers, the A549 line-specific EV proteins CD109 and PTGFRN were found to be metastasis-associated in lung cancer." (PMID 32916986, 2020). "Targeting CD109 could provide therapeutic benefits against lung cancer metastasis and drug resistance." (PMID 33375719, 2020). "Additionally, CD109 acts as a metastatic driver in lung cancer via regulating JAK/STAT3." (PMID 33375719, 2020). "Moreover, elevation of CD109 was accompanied by upregulation of the yes-associated protein (YAP) signature in metastatic lung cancer cells and lung cancer patients, and activation of YAP was demonstrated to participate in CD109-elicited EMT gene expressions and tumor invasiveness." (PMID 33375719, 2020). "Thus, we further evaluated the involvement of CD109 in stemness properties in lung cancer cells." (PMID 33375719, 2020).
hepatocellular carcinoma (6 papers, 2016 to 2024). A malignant tumor that arises from hepatocytes. "For example, CD109 expression determined by immunohistochemistry in tumour specimens from patients with myxofibrosarcoma and hepatocellular carcinoma was associated with a poorer prognosis in such patients." (PMID 29731998, 2018). "In hepatocellular carcinoma, CD109 plays a pivotal role in the interaction between tumor-associated endothelial cells (TEC) and the tumor microenvironment, particularly in the context of inflammation and immune response." (PMID 39990858, 2024). "The effect of human umbilical vein endothelial cells (HUVEC) with different CD109 expression on hepatoma cell proliferation, migration, and invasion was compared in co-culture assay." (PMID 27121053, 2016). "Sporadic expression of CD109 can be detected on a few human hepatoma cell lines, and it is highly expressed on HUVEC by quantitative real-time PCR (qRT-PCR), Western Blotting (WB), and immunofluorescence staining." (PMID 27121053, 2016). "CD109 knockdown in HUVEC promoted hepatoma cell proliferation, migration, and invasion." (PMID 27121053, 2016). "Reduced CD109 expression on tumor-associated endothelial cells (TEC) is linked to advanced tumor features, including larger size, microvascular invasion, and increased tumor progression, proliferation, migration, and hepatoma cell invasion via enhanced IL-8 secretion." (PMID 39990858, 2024). "CD109 has been identified as an important regulator of the Epithelial–mesenchymal transition (EMT pathway), and has also been found to be down-regulated in more advanced stage hepatocellular carcinoma." (PMID 30634628, 2019). "We investigated the function of CD109 in TEC and its clinical significance in hepatocellular carcinoma (HCC)." (PMID 27121053, 2016).
nasopharyngeal carcinoma (6 papers, 2016 to 2025). A carcinoma arising from the nasopharyngeal epithelium. "Our research group in the early stage identified CD109 as the target of aptamer S3 in nasopharyngeal carcinoma (NPC)." (PMID 38087297, 2023). "Similar signaling pathways have been observed in tumor cells, where FLOT2 upregulates CD109 by stabilizing the expression of STAT3, inhibiting the TGF-β signaling pathway and promoting the development of nasopharyngeal carcinoma." (PMID 41327642, 2025). "It is suggested that serum CD109+ and EGFR+ EVs could be used as biomarkers for nasopharyngeal cancer." (PMID 36968209, 2023). "The TEV proteins, CD109, and epidermal growth factor receptor (EGFR) are present in nasopharyngeal carcinoma (NPC), and all markers decrease significantly after radiotherapy, suggesting their role in NPC diagnosis." (PMID 35164379, 2022).